RSBN1L (round spermatid basic protein 1 like)
Description:
Lysine-specific demethylase that specifically demethylates methylated lysine residues of proteins.
Synonyms: FLJ42526; FLJ45813; MGC71764
Tractability: PROTAC: UniProt records ubiquitination sites on it; ubiquitination databases record sites on it; its protein half-life has been measured.
Gene: Protein-coding gene on chromosome 7 (77,696,459 to 77,783,022, forward strand). Ensembl gene ENSG00000187257.
Subcellular location: Nucleus
Subcellular location (Human Protein Atlas): Nuclear speckles; Plasma membrane
Gene Ontology:
Molecular function: protein demethylase activity
Cellular component: nuclear speck; nucleus
Genetic constraint (gnomAD): Loss-of-function variants: 20 observed, 51.91 expected, observed/expected ratio (o/e) 0.39, 90% interval 0.27 to 0.56. The upper end of that interval is the gene's LOEUF score, 0.56, which puts it in group 2 of 6, group 1 being the genes least tolerant of losing a copy. Missense variants: 910 observed, 972.02 expected, observed/expected ratio (o/e) 0.94, 90% interval 0.89 to 0.99. Synonymous variants: 406 observed, 377.25 expected, observed/expected ratio (o/e) 1.08, 90% interval 0.99 to 1.17.
Homologues: Orthologues: chimpanzee RSBN1L (99% identical), macaque RSBN1L (98% identical), pig RSBN1L (91% identical), dog RSBN1L (90% identical), mouse Rsbn1l (81% identical), rat Rsbn1l (81% identical), rabbit RSBN1L (78% identical), guinea pig RSBN1L (73% identical), tropical clawed frog rsbn1l (59% identical), Drosophila melanogaster CG10600 (34% identical), Caenorhabditis elegans dpy-21 (28% identical). Paralogues in human: RSBN1 (44% identical).
Diseases named in the same sentence as RSBN1L in open-access papers:
RSBN1L is named in the same sentence as 2 diseases in open-access papers, as found by Europe PMC text mining. Sharing a sentence is not in itself a finding about the gene and the disease.
RSBN1L shares sentences with these, for which no sentence is quoted: bladder cancer (1 paper); tumor (1).